TSHR (thyroid stimulating hormone receptor)
Diseases named in the same sentence as TSHR in open-access papers (continued):
Sharing a sentence is not in itself a finding about the gene and the disease.
Graves disease (continued). "This is the first complete report of a case of new-onset Graves’ disease after starting nivolumab therapy, confirmed by diffusely increased thyroid uptake in scintigraphy and the positive conversion of antibodies against thyroid-stimulating hormone receptor." (PMID 32847555, 2020). "The development of an animal model for Graves’ disease is dependent on the immunization against the human TSHR, providing compelling evidence for the TSHR abeing the primary autoantigen of the disease." (PMID 32399893, 2020). "Graves’ disease (GD) is an autoimmune condition with the appearance of anti-TSH receptor (TSHR) autoantibodies in the serum." (PMID 32399893, 2020). "We sampled PBMCs from eight patients with Graves’ disease and eight normal controls, and stained surface TRAb by recombinant human TSHR and anti-human TSHR antibody to the C terminus." (PMID 33260824, 2020). "There are several practical in vivo applications of targeting the TSHR with K1-70 including controlling thyroid overactivity in Graves’ disease and GO." (PMID 32472423, 2020). "Patients with Graves’ disease have TSHR autoantibodies called TRAbs that bind TSHR competitively with TSH." (PMID 33260824, 2020). "TSHR also serves as an autoantigen in Graves’ disease, where autoantibody binding leads to activation of the downstream signaling cascades, mimicking the effect of consistent stimulation of TSH and thus resulting in hyperthyroidism." (PMID 32698392, 2020). "Lipolysis of WAT leads to elevated plasma free FA in Graves’ disease as a consequence of TSHR activation and hyperthyroidism, which are also major contributors for GO development." (PMID 33266331, 2020). "As well as cost implications and the potential risk of immunocompromise with the non–TSHR-specific therapies, it remains unclear whether they will ameliorate the long-term risk of hypothyroidism, reduce goiter, or indeed prevent a late relapse of Graves’ hyperthyroidism." (PMID 32845332, 2020). "Autoantibodies with TSHR antagonistic activities are “natural” inhibitors of TSHR stimulation and are expected to be helpful in controlling TSHR activity in patients with Graves’ disease, Graves’ ophthalmopathy and thyroid cancer." (PMID 32472423, 2020). "Autoimmunity to the thyroid-stimulating hormone receptor (TSHR) plays the central role for the pathogenesis of Graves’ disease (GD)." (PMID 32399893, 2020). "Examples for the pathogenic effects of high GPCR abs are discussed before such as for Graves’ disease showing increased TSHR abs also leading to tissue inflammation." (PMID 33384684, 2020). "The cause of Graves' disease is that when MHC class II is demonstrated in the epithelial cell of the thyroid, T cells recognize the thyroid-stimulating hormone receptor (TSHR) as an extrinsic antigen and create autoantibodies from the B cell." (PMID 31636683, 2019). "Graves' disease (GD) involves the presence of agonistic auto-antibodies against the thyrotropin receptor (TSHR), which are responsible for the clinical symptoms." (PMID 31379878, 2019). "This study explores the first-in-human use of antigen-specific immunotherapy with a combination of two thyrotropin receptor (TSHR) peptides (termed ATX-GD-59) in Graves' hyperthyroidism." (PMID 31194638, 2019). "Graves' disease (GD) is a highly prevalent autoimmune disease characterized by the presence of agonistic auto-antibodies against the thyrotropin receptor (TSHR), which are responsible for hyperthyroidism and extrathyroidal manifestations." (PMID 31379878, 2019). "GO and Graves’ disease share a common immunopathogenesis, which is initiated by T cell intolerance to thyrotropin receptor (TSHR)." (PMID 31270379, 2019). "Identification of “neutral” TSHR antibodies in patients with Graves' disease, therefore, suggests their potential involvement in the disease process." (PMID 30666231, 2018).
Graves disease (continued). "Experimental mouse models of autoimmune hyperthyroidism have been reported where in vivo expression of the extracellular region of the human TSHR (termed hTSHR A-subunit) by genetic immunizytion leads to the induction of experimental GD in the female model." (PMID 30166557, 2018). "Graves’ orbitopathy (GO) is an eye disease occurring mainly in patients with Graves’ disease (GD), in which autoantibodies (TRAB) to the thyrotropin receptor (TSHR) cause hyperthyroidism." (PMID 29849043, 2018). "TSHR autoantibodies are hallmarks for human autoimmune thyroid disease (AITD) which encompasses both Graves' disease and Hashimoto's thyroiditis, but are heterogeneous in function." (PMID 30666231, 2018). "The thyroid stimulating hormone receptor (TSHR) is the major regulator of thyroid gland function and also a major autoantigen in Graves' disease (GD) which is caused by stimulating TSHR autoantibodies inducing thyroid gland hyperactivity." (PMID 30666231, 2018). "The TSHR is a target autoantigen in Graves’ disease (GD), where TSHR autoantibodies (TRAbs) induce thyroid growth and hyperthyroidism and represent an important diagnostic hallmark." (PMID 29435670, 2018). "Both sexes comparably developed autoimmune hyperthyroidism characterized by TSHR stimulating autoantibodies, elevated T4 values, hyperplastic thyroids and hearts." (PMID 30166557, 2018). "In Graves’ Disease, B cells play a vital role as they are the source of pathognomonic activating autoantibodies (TRAb) against thyroid-stimulating hormone receptor (TSHR)." (PMID 29449887, 2018). "According to them, TSHR-Abs offer skeletal protection in hyperthyroid Graves' disease, even in the face of high thyroid hormone and low TSH levels." (PMID 29768627, 2018). "The diagnosis of Graves’ disease is based on the detection of circulating auto-antibodies against thyroid stimulating hormone receptor (TSHR) in patient’s blood." (PMID 30018377, 2018). "Patients with Graves’ disease develop autoantibodies that bind the extracellular domain (ECD) of the TSHR and activate the receptor." (PMID 27921237, 2017). "Graves’ disease is a common antibody-mediated autoimmune condition targeting the thyrotropin-TSH receptor (TSHR) in the thyroid gland, resulting in hyperthyroidism, with an annual incidence of 15–80 per 100,000 persons throughout the world." (PMID 27368808, 2017). "LGR4, which is expressed in the CNS, particularly in the spinal cord, and also in other sites throughout the body, notably the skin and gastrointestinal tract, is a homolog of TSHR, the target of autoantibodies in Graves’ disease." (PMID 28533776, 2017). "In a study including 62 pregnant women with Graves’ disease, TRAbs were measured by four immunoassays: first generation, second generation using porcine TSHR, second generation using human recombinant TSHR, and third generation." (PMID 28713331, 2017). "The challenge in Graves’ disease is to specifically inhibit the development, or ongoing production, of TSHR autoantibodies." (PMID 28620373, 2017). "The thyroid-stimulating hormone receptor (TSHR) is the target autoantigen for TSHR-stimulating autoantibodies in Graves’ disease." (PMID 27921237, 2017). "Various approaches have been used to model human Graves’ disease in mice, including transfected fibroblasts, and plasmid or adenoviral immunisations with the extracellular A subunit of the human thyrotropin receptor (TSHR)." (PMID 27368808, 2017). "After some failed efforts to use plasmid immunisations, adenovirally induced immunisation with the A domain of TSHR (Ad-TSHR) in BALB/c mice was successfully established to induce a mouse model of Graves’ disease." (PMID 27368808, 2017). "Graves’ disease (GD) is an organ specific autoimmune disease, characterized by the presence of autoantibodies directed against the thyrotropin receptor (TSHR)." (PMID 28319174, 2017).
Graves disease (continued). "A long-term model for human Graves’ disease was established in mice using continuing immunisations (4-weekly injections) with recombinant adenovirus expressing TSHR." (PMID 27368808, 2017). "Graves’ disease is an autoimmune thyroid disorder characterized by hyperthyroidism, and patients exhibit thyroid-stimulating hormone receptor antibody." (PMID 28162094, 2017). "Insight into the mechanism of activation of the TSHR by both TSH and TSHR autoantibodies is likely to be useful in the development of new treatments for Graves’ disease." (PMID 27921237, 2017). "The highly glycosylated extracellular TSHR A-subunit, formed by intramolecular cleavage of the holoreceptor, is shed and is the autoantigen primarily responsible for TSAb induction in Graves’ disease." (PMID 28620373, 2017). "TRAbs that induce a strong TSH-like stimulatory signal are referred to as TSHR-stimulating antibodies/immunoglobulin (TSAbs/TSI), which is the immunological hallmark of Graves’ disease." (PMID 27895620, 2016). "For a long time there was no robust animal model for TED, with none of the models being felt to exhibit the full spectrum of Grave’s disease or demonstrate a primary role for the Thyroid Stimulating Hormone Receptor (TSH-R) as an orbital target antigen." (PMID 26774505, 2016). "By adapting the adenovirus vector to express the TSHR A subunit instead of full-length TSHR, the incidence of induced Graves’ disease was increased to approximately 65–80% in female BALB/c mice." (PMID 27895620, 2016). "The characteristic hyperthyroidism in Graves’ disease is due to the presence of stimulating antibodies although blocking and cleavage region (or neutral) antibodies to the TSHR are also produced in many patients." (PMID 26858688, 2016). "For example, intraperitoneal immunization with TSHR-expressing M12 (B cells) induced Graves’ hyperthyroidism with TSAbs in 100% of immunized BALB/c mice." (PMID 27895620, 2016). "After human TSHR was cloned, similar attempts were made to induce Graves’ disease by immunizing animals with human TSHR that was expressed either in a baculovirus expression system or in insect cells, or purified from cloned human thyroid cells (GEJ)." (PMID 27895620, 2016). "The thyroid-stimulating hormone (TSH) receptor (TSHR) is the autoantigen responsible for the hyperthyroidism in Graves’ disease and is considered an important contributor to GO." (PMID 26062519, 2016). "The data indicated that the TSHR-Glo assay provides a sensitive (limits of detection: 10–100 mIU/l) and a selective assay for also measuring agonist-like responses in Graves’ disease patient’s sera." (PMID 26858688, 2016). "Since the discovery 60 years ago of the “long-acting thyroid stimulator” by Adams and Purves, great progress has been made in the detection of thyroid-stimulating hormone (TSH) receptor (TSHR) autoantibodies (TRAbs) in Graves’ disease." (PMID 27504107, 2016). "Graves’ disease is marked by the production of different autoantibodies directed against the ectodomain of the TSHR." (PMID 26858688, 2016). "Thyroid-stimulating hormone receptor antibodies (TRAb) are present in all patients with Graves’ disease, and the severity and the activity of GO directly correlate positively with the blood TRAb levels." (PMID 26062519, 2016). "Graves disease is an autoimmune condition in which autoantibodies bind to the thyrotropin receptor (TSHR) on thyrocytes, leading to increased thyroid hormone production." (PMID 26087256, 2015). "The circulating TSHR antibody in Graves’ disease presumably has a stimulatory effect on the thyroid tissue in the ovary, resulting in gradual growth and increased thyroid hormone production." (PMID 26530865, 2015). "Second, in patients with coexisting Graves’ disease, TSHR antibodies stimulate the struma ovarii in the same way that they stimulate the thyroid tissue to cause Graves’ disease." (PMID 26530865, 2015).
Graves disease (continued). "The relationship between TSHR antibodies and serum bone turnover markers were analyzed in untreated premenopausal patients with Graves’ disease." (PMID 26650844, 2015). "For instance, in Graves’ disease, thyroid stimulating hormone receptor antibodies (TSHR-Ab) bind thyroid stimulating hormone receptor (TSHR) and activate it, leading to hyper-secretion, hypertrophy, and hyperplasia of the thyroid follicles." (PMID 25541933, 2014). "Graves' orbitopathy (GO) as well as Graves' disease (GD) hyperthyroidism originate from an autoimmune reaction against the common auto-antigen, thyroid-stimulating hormone receptor (TSHR)." (PMID 25061884, 2014). "Since many patients with Graves' disease have stimulating, blocking and neutral TSHR-Abs, their interplay during the immune suppression of pregnancy can be extremely complex." (PMID 23691429, 2013). "Thyroid stimulating hormone receptor (TSH-R) is the prime autoantigen in Graves' disease and atrophic thyroiditis." (PMID 23878745, 2013). "The measurement of autoantibodies to thyroid-stimulating hormone receptor (TSHR) is important for the diagnosis of autoimmune thyroid disease such as Graves’ disease (GD)." (PMID 23852019, 2013). "The TSHr-Ab assay has therefore to be considered as a useful tool to reveal subclinical autoimmune hyperthyroidism whenever TSH is below the normal range, even if TPO-Abs are negative and there is no other sign of endocrine autoimmunity." (PMID 22654905, 2012). "This direct role of anti-TSHR antibodies in Graves' disease aetiology motivated the measurement, in the same collection of T1D cases, of TPOA (n = 8,300), which was an assay available at a significantly lower cost than the anti-TSHR autoantibody test." (PMID 21829393, 2011). "Graves' disease can be induced in mice by injecting cells expressing the human TSHR or immunization with the human TSHR DNA in plasmid or adenovirus vectors." (PMID 21738647, 2011). "In conclusion, investigations in AXBXA recombinant inbred mice immunized with TSHR A-subunit adenovirus provided unexpected insight into several aspects of Graves' disease." (PMID 21738647, 2011). "Recombinant inbred AXBXA strains immunized with TSHR A-subunit adenovirus provided insight into two aspects of Graves' disease." (PMID 21738647, 2011). "In contrast with T1D, Graves' disease is known to be mediated by autoantibodies against the thyroid stimulating hormone receptor (TSHR), which leads to hypothyroidism." (PMID 21829393, 2011). "Second, our data are the first to implicate MHC class I genes as contributing to the variability in the TSHR antibody response in an induced mouse model of Graves' disease." (PMID 21738647, 2011). "Both disease are characterized by lymphocytic infiltration and the presence of serum anti-thyroperoxydase antibody (TPOAb) and/or anti-thyroglobulin antibody (TgAb) for Hashimoto's thyroiditis and TSH receptor autoantibodies (TSHR-Ab) for Graves' disease." (PMID 19138419, 2009). "Graves disease (GD) affects 0.5–1% of the general population, and results from the presence of autoantibodies to the thyroid-stimulating hormone receptor (TSHR), leading to over-activity of the thyroid gland." (PMID 19284637, 2009). "In Graves' disease, autoantibodies to the TSHR (TSHR-Abs)stimulate the TSHR to produce thyroid hormone excessively." (PMID 16050145, 2005). "In summary, our results demonstrate that the new automated bridge assay for detecting thyroid-stimulating hormone receptor autoantibodies has high sensitivity and specificity for diagnosing Graves' disease and to discriminate from other thyroid diseases, respectively." (PMID 41730272, 2026). "The aim of the present study was to evaluate a new automated bridge chemiluminescence thyroid-stimulating hormone receptor autoantibody assay for the diagnosis and in the follow-up of Graves' disease patients and to compare this assay with another established competition assay." (PMID 41730272, 2026).
Graves disease (continued). "However, TSHR CAAR T cells showed reduced cytotoxicity against anti-TSHR B cells in the plasma of Graves’ disease patients compared to healthy plasma." (PMID 41357209, 2025). "However, a positive effect was observed in patients with Graves’ disease, evidenced by a significant reduction in thyroid-stimulating hormone receptor antibody levels." (PMID 39940263, 2025). "Graves’ disease (GD) is a prototypical organ-specific autoimmune thyroid disorder characterized by hyperthyroidism mediated by thyroid-stimulating hormone receptor autoantibodies (TRAb), along with thyroid follicular epithelial hyperplasia and lymphocytic infiltration of the gland." (PMID 41035651, 2025). "However, under specific conditions such as activation by TSHR antibodies in Graves’ disease, TSHR signaling is mediated through Gαq/11." (PMID 41373675, 2025). "Therefore, for early detection and launch of specific treatment of Graves’ disease, screening for thyroid hormone and anti-thyroid stimulating hormone receptor antibody levels is necessary when treating patients with periodic paralysis." (PMID 39088436, 2024). "Graves’ disease is triggered by the decrease of immune tolerance to the thyroid-stimulating hormone receptor (TSHR), with its specificity and core mechanism centered on the activation of immunoglobulin G subclass antibodies against TSHR (TRAb)." (PMID 39872521, 2024). "Graves’ disease (GD) is an autoimmune disorder that develops because thyroid receptor autoantibodies (TRAbs) stimulate the thyroid-stimulating hormone (TSH) receptor (TSHR) on the thyroid gland." (PMID 35831126, 2023). "Grave’s disease is another common T-cell-mediated autoimmune hyperthyroidism characterized by the presence of autoantibodies directed toward the thyroid-stimulating hormone receptor (TSHR), resulting in an excessive production of thyroid hormones." (PMID 37508347, 2023). "However, Graves’ disease stimulates the production of TSHR antibodies, leading to the development of hyperthyroidism." (PMID 37686882, 2023). "As a central link receptor of the HPT, TSHR is a member of the G-protein-coupled receptor (GPCRs) superfamily, the main antigen of autoimmune thyroid diseases, and can be used as a drug target for Graves’ disease (GD)." (PMID 38111381, 2023). "In some of these patients anti-TSHR antibodies persist particularly after radioiodine therapy, and therefore extrathyroidal manifestations can also occur later in the course of these cases with Graves’ disease." (PMID 37082124, 2023). "Graves’ disease is diagnosed through patient history and clinical examination and confirmed through biochemical tests which detect elevated thyroid hormones and thyroid-stimulating hormone receptor antibodies (TSH-R-Ab)." (PMID 38203243, 2023). "Diagnosis of Graves’ disease can be confirmed through the detection of TSHR antibodies." (PMID 36830848, 2023). "The basis of the development of AITD - Hashimoto’s thyroiditis (HT), Graves’ disease (GD), Graves’ ophthalmopathy (GO) is the loss of immune tolerance to thyroid antigens - thyroid peroxidase (TPO), thyroglobulin (Tg) and thyroid-stimulating hormone receptor (TSH-R)." (PMID 37711890, 2023). "Likewise, while thyroid-stimulating hormone receptor (TSHR) is the most common autoantigen in Graves' disease, it is also found in a small number of Hashimoto's disease patients." (PMID 35911325, 2022). "Graves’ disease is associated with the development of autoantibodies targeting the TSH receptor (TRAb, anti-TSHR antibodies) which may be stimulating, blocking, or bio-inactive in nature." (PMID 35588090, 2022). "Typically, Graves’ disease patients exhibit a spectrum of different TSHR antibodies, in rare cases also with receptor blocking properties, which may change in the course of the disease and in sum determine thyroid gland activity." (PMID 35175936, 2022).